NPIPA3 (nuclear pore complex interacting protein family member A3)
Tractability: No criterion of Open Targets' tractability assessment is met for any kind of drug.
Gene: Protein-coding gene on chromosome 16 (14,703,411 to 14,726,342, forward strand). Ensembl gene ENSG00000224712.
Subcellular location (Human Protein Atlas): Nucleoplasm
Homologues: Paralogues in human: NPIPA2 (99% identical), NPIPA1 (89% identical), NPIPA6 (88% identical), NPIPA9 (88% identical), NPIPA7 (88% identical), NPIPA8 (88% identical), NPIPA5 (83% identical), NPIPB4 (75% identical), NPIPB5 (75% identical), NPIPB12 (74% identical), NPIPB13 (74% identical), NPIPB11 (74% identical), and 7 more.
Diseases named in the same sentence as NPIPA3 in open-access papers:
NPIPA3 is named in the same sentence as 1 disease in open-access papers, as found by Europe PMC text mining. Sharing a sentence is not in itself a finding about the gene and the disease. The quoted sentences say what the papers report.
age-related macular degeneration (1 paper, 2015). Age-related loss of vision in the central portion of the retina (macula), secondary to retinal degeneration. "NPIPA3 is a member of the NPIP gene family, members of which are expressed in the macula and have been proposed as a susceptibility locus for age-related macular degeneration." (PMID 26335491, 2015).